IFT57 (intraflagellar transport 57)
Description:
Required for the formation of cilia. Plays an indirect role in sonic hedgehog signaling, cilia being required for all activity of the hedgehog pathway (By similarity). Together with RAB23 and KIF17, it is required for the localization of specific G protein-coupled receptors, such as dopamime receptor DRD1, to primary cilia. Has pro-apoptotic function via its interaction with HIP1, leading to recruit caspase-8 (CASP8) and trigger apoptosis. Has the ability to bind DNA sequence motif 5'-AAAGACATG-3' present in the promoter of caspase genes such as CASP1, CASP8 and CASP10, suggesting that it may act as a transcription regulator; however the relevance of such function remains unclear.
Synonyms: ESRRBL1; HIPPI; FLJ10147; MHS4R2; OFD18
Tractability: PROTAC: ubiquitination databases record sites on it; its protein half-life has been measured.
Gene: Protein-coding gene on chromosome 3 (108,160,812 to 108,222,553, reverse strand). Ensembl gene ENSG00000114446.
Subcellular location: Cell projection, cilium; Cytoplasm, cytoskeleton, cilium basal body
Subcellular location (Human Protein Atlas): Basal body; Golgi apparatus; Mid piece; Primary cilium; Centriolar satellite; Cytosol; Primary cilium transition zone
Pathways (Reactome):
Organelle biogenesis and maintenance: Intraflagellar transport
Signal Transduction: Hedgehog 'off' state
Gene Ontology:
Molecular function: protein binding
Biological process: apoptotic process; regulation of apoptotic process; cilium assembly; intraciliary anterograde transport; intraciliary transport; non-motile cilium assembly
Cellular component: ciliary base; intraciliary transport particle A; intraciliary transport particle B; photoreceptor connecting cilium; ciliary basal body; ciliary tip; cilium; Golgi apparatus; microtubule organizing center; axoneme; centrosome; dendrite terminus
Genetic constraint (gnomAD): Loss-of-function variants: 24 observed, 23.68 expected, observed/expected ratio (o/e) 1.01, 90% interval 0.73 to 1.42. The upper end of that interval is the gene's LOEUF score, 1.42, which puts it in group 5 of 6, group 1 being the genes least tolerant of losing a copy. Missense variants: 257 observed, 300.22 expected, observed/expected ratio (o/e) 0.86, 90% interval 0.77 to 0.95. Synonymous variants: 124 observed, 117.25 expected, observed/expected ratio (o/e) 1.06, 90% interval 0.91 to 1.23.
Gene-disease validity (ClinGen):
ClinGen rates the evidence that IFT57 causes each of these diseases.
ciliopathy (autosomal recessive): Moderate. A genetic disorder of the cellular cilia or the cilia anchoring structures, the basal bodies, or of ciliary function.
Homologues: Orthologues: chimpanzee IFT57 (99% identical), macaque IFT57 (99% identical), pig IFT57 (92% identical), dog IFT57 (91% identical), rat Ift57 (91% identical), mouse Ift57 (90% identical), guinea pig IFT57 (90% identical), rabbit IFT57 (82% identical), tropical clawed frog ift57 (72% identical), zebrafish ift57 (60% identical), Caenorhabditis elegans che-13 (36% identical), Drosophila melanogaster IFT57 (32% identical).
Diseases named in the same sentence as IFT57 in open-access papers:
IFT57 is named in the same sentence as 37 diseases in open-access papers, as found by Europe PMC text mining. Sharing a sentence is not in itself a finding about the gene and the disease. The quoted sentences say what the papers report.
Bardet-Biedl syndrome (3 papers, 2009 to 2025). A ciliopathy with multisystem involvement. "We examined the genes IFT57 (mutated in orofaciodigital syndrome (OFD, OMIM #311200)), BBS2 (Bardet-Biedl syndrome (BBS, OMIM #209900)), (TMEM231 (Meckel-Gruber syndrome (MKS, OMIM #249000)), TCTN2 (Joubert syndrome, (JBTS, OMIM #213300))." (PMID 32445086, 2020). "The resemblance of both cep70 and cep131 morphants to those of zebrafish IFT57 and IFT88 makes the two proteins candidates for genes mutated in inherited human diseases similar to Bardet-Biedl syndrome in which cilia in a number of tissues are affected." (PMID 19254375, 2009).
anaplastic thyroid carcinoma (1 paper, 2024). "CD47 and IFT57 mRNA expression were consistently higher in 8505C anaplastic thyroid carcinoma cells relative to Nthy-ori-3-1 normal thyroid follicular epithelial cells and other available thyroid carcinoma cell lines." (PMID 39201643, 2024).
breast carcinoma (1 paper, 2024). "Breast carcinomas and uveal melanoma also showed significant correlations between higher IFT57 expression above the mean and improved overall survival that were not significant for CD47." (PMID 39201643, 2024).
cutaneous melanoma (1 paper, 2024). A primary melanoma arising from atypical melanocytes in the skin. "Correspondingly, CD47 was ranked 432nd for coexpression with IFT57 in cutaneous melanoma." (PMID 39201643, 2024).
glioblastoma (1 paper, 2024). The most malignant astrocytic tumor (WHO grade IV). "Overexpression of IFT57 sensitized glioblastoma cells to apoptotic cell death, whereas silencing IFT57 in H157 lung carcinoma and A549 oral squamous carcinoma cells inhibited cell proliferation and increased apoptosis." (PMID 39201643, 2024).
glioma (1 paper, 2024). A benign or malignant brain and spinal cord tumor that arises from glial cells (astrocytes, oligodendrocytes, ependymal cells). "CRACD expression greater than the mean achieved significance in 6 of the 29 tumor types, including 3 where IFT57 was most significantly associated with overall survival: lower-grade glioma, lung adenocarcinoma, and papillary thyroid carcinoma." (PMID 39201643, 2024). "CRACD mRNA expression inversely correlated with IFT57 mRNA and with survival in low-grade gliomas, lung adenocarcinomas, and papillary thyroid carcinomas, suggesting that IFT57 rather than CD47 regulates survival in these cancers." (PMID 39201643, 2024). "Consistent with the improved overall survival associated with higher IFT57, higher CRACD mRNA in low-grade glioma was associated with decreased overall survival (67 versus 114 months, p = 4 × 10−4)." (PMID 39201643, 2024). "IFT57 mRNA higher than the median was also significantly correlated with decreased overall survival in low-grade glioma and lung squamous carcinoma." (PMID 39201643, 2024). "The primary cilium also regulates cancer pathogenesis, and correlations between IFT57 mRNA and survival paralleled those for CD47 in thyroid and lung carcinomas, melanoma, and glioma." (PMID 39201643, 2024).
head and neck squamous cell carcinoma (1 paper, 2024). A squamous cell carcinoma that arises from any of the following anatomic sites: lip and oral cavity, nasal cavity, paranasal sinuses, pharynx, larynx, and salivary glands. "Head and neck squamous cell carcinoma also showed significant correlations between IFT57 mRNA expression higher than the mean and decreased overall survival that was not significant for CD47." (PMID 39201643, 2024).
lung adenocarcinoma (1 paper, 2024). A carcinoma that arises from the lung and is characterized by the presence of malignant glandular epithelial cells. "Higher IFT57 mRNA expression in lung adenocarcinomas was associated with improved overall survival." (PMID 39201643, 2024). "This was consistent with IFT57 being the top-ranked gene for coexpression with CD47 in lung adenocarcinoma and a previous analysis of TCGA data." (PMID 39201643, 2024). "Neither CD47 nor IFT57 mRNA expression was significantly correlated with overall survival in lung adenocarcinoma using a median cutoff." (PMID 39201643, 2024).
lung carcinoma (1 paper, 2024). "CD47 was the top-ranked gene co-expressed with IFT57 in breast, bladder, ovarian, endometrial, thyroid, and lung carcinomas." (PMID 39201643, 2024).
neuroendocrine tumors (1 paper, 2024). "Significant positive correlations between CD47 and IFT57 mRNA expression extended to neuroendocrine tumors, sarcomas, and some hematologic malignancies, but IFT57 and CD47 co-expression had lower Spearman’s coefficients and rank orders in these cancers." (PMID 39201643, 2024).
non-small cell lung carcinoma (1 paper, 2025). A group of at least three distinct histological types of lung cancer, including non-small cell squamous cell carcinoma, adenocarcinoma, and large cell carcinoma. "IFT57 exerts an oncogenic role in non-small cell lung cancer by activating DNA replication and cell cycle pathways via upregulation of MCM2, MCM6, and MCM8 expression." (PMID 40145017, 2025).
ovarian carcinoma (1 paper, 2021). A malignant neoplasm originating from the surface ovarian epithelium. "Eight immune factors (IFT57, MAL, ANXA4, SCRN1, LTBR, KIFAP3, HSPA5, and LTN1) were positively correlated with poor prognosis of ovarian cancer, whereas six immune factors (PSMB9, FOXJ1, CTSH, MIF, CTSD, and PSMB8) were negatively correlated with poor prognosis of ovarian cancer." (PMID 34109184, 2021).
papillary thyroid carcinomas (1 paper, 2024). "Conversely, transient overexpression of IFT57 by plasmid transfection resulted in a lower increase in CD47 mRNA expression in MDA-T68 follicular variant of papillary thyroid carcinoma cells than induced by transfection with the empty vector." (PMID 39201643, 2024). "Genes with at least 8-fold changes in IFT57 knockdown cells were analyzed, and those with coexpression p-values < 10−4 in papillary thyroid carcinomas are listed." (PMID 39201643, 2024). "Of the 41 overlapping genes, 11 were significantly correlated with mRNA expression of both CD47 and IFT57 in TCGA papillary thyroid carcinomas, but only 5 of the latter were consistent with the direction of change in the IFT57 knockdown cell lines." (PMID 39201643, 2024). "CD47 ranked first for coexpression with IFT57 mRNA in papillary thyroid carcinomas, and higher expression of both genes correlated with significantly improved overall survival." (PMID 39201643, 2024). "CD47 was top-ranked for IFT57 mRNA coexpression in papillary thyroid carcinomas, with a Spearman coefficient r = 0.62." (PMID 39201643, 2024). "Papillary thyroid carcinomas exhibited strong associations between survival and expression of CD47 or IFT57." (PMID 39201643, 2024). "Consistent with its inverse coexpression with IFT57 in thyroid carcinoma cells in vitro, CRACD mRNA expression above the mean was associated with significant decreases in both disease-free and overall survival in TCGA papillary thyroid carcinomas." (PMID 39201643, 2024).
renal carcinoma (1 paper, 2024). A carcinoma arising from the epithelium of the renal parenchyma or the renal pelvis. "Two renal carcinoma datasets and a pediatric AML dataset showed significant correlations between CRACD and overall survival that may be independent of IFT57 regulation." (PMID 39201643, 2024).
retina degeneration (1 paper, 2022). "A major finding is that IFT88, IFT57 and IFT140 are depleted gradually after deletion of CEP164 at P16-P21, implicating IFT malfunction as the cause of retina degeneration in rodCep164-/- mice." (PMID 36074756, 2022).
thyroid cancer (1 paper, 2024). "Based on these data, we selected 8505C cells to identify genes that are differentially regulated by CD47 or IFT57 in thyroid cancers." (PMID 39201643, 2024). "We were more interested in identifying genes with expression that is selectively regulated by IFT57 in thyroid cancer cells." (PMID 39201643, 2024). "Transcriptome analysis following knockdown of CD47 or IFT57 in thyroid carcinoma cells identified the cytoskeletal regulator CRACD as a specific target of IFT57." (PMID 39201643, 2024). "In contrast, most of the genes identified to be dependent for their mRNA expression only on IFT57 in thyroid carcinoma cells were nonetheless significantly coexpressed with CD47 and IFT57 in papillary thyroid tumors." (PMID 39201643, 2024). "The coregulation of IFT57 with CD47 defined here in thyroid carcinomas generalizes to survival effects in some additional cancer types but is not universal to all malignancies." (PMID 39201643, 2024). "CD47 and IFT57 mRNAs were coordinately regulated in thyroid carcinoma cell lines." (PMID 39201643, 2024). "Notably, these candidate IFT57-dependent genes have reported functions in other cancers, and roles for GAS6 and NID2 have been reported in thyroid cancer." (PMID 39201643, 2024). "This divergence could involve upstream factors that modulate IFT57 target genes secondary to coregulating CD47 and IFT57 expression either in the thyroid carcinoma cells or in tumor stromal cells." (PMID 39201643, 2024). "The present results identify distinct gene sets that are regulated by decreasing the expression of CD47 or IFT57 in thyroid carcinoma cells in vitro, but many of these genes exhibit strong correlations with both CD47 and IFT57 mRNA expression in thyroid tumors." (PMID 39201643, 2024). "Although expression of these genes was sensitive to loss of IFT57 but not CD47 in thyroid carcinoma cells, a majority showed positive or negative coexpression with CD47 mRNA in the tumors that paralleled their IFT57 coexpression (e.g., RAMP1)." (PMID 39201643, 2024). "Similarly, treatment of MDA-T68 thyroid carcinoma cells with 10 μM JQ1 significantly decreased mRNA for long and short isoforms of CD47, with a parallel time-dependent decreasing trend in mRNA expression for IFT57 mRNA." (PMID 39201643, 2024). "IFT57 and CD47 mRNA expression were positively correlated across the 11 thyroid carcinomas but did not achieve significance (R2 = 0.18, p = 0.2)." (PMID 39201643, 2024). "We identified several genes that are specifically regulated by IFT57 but not CD47 knockdown in the 8505C thyroid carcinoma cells, and of these, CRACD showed the highest specificity for dependence on IFT57 but not CD47 mRNA expression in papillary thyroid tumors." (PMID 39201643, 2024).
thyroid tumor (1 paper, 2024). A benign or malignant neoplasm affecting the thyroid gland. "Presumably, coexpression of these genes in thyroid tumors is mediated by factors that coordinately induce both CD47 and IFT57 mRNA expression." (PMID 39201643, 2024).
tumor (4 papers, 2015 to 2025). "An alternate hypothesis is suggested by an analysis presented here of transcripts coexpressed with CD47 mRNA in TCGA RNAseq data for 29 tumor types, which identified intraflagellar transport-57 (IFT57) as a top CD47-coexpressed gene." (PMID 39201643, 2024). "Analysis of the expression of the TILB-related signature genes in B Plasma cells showed that KMO, IFT57, HDAC9, GSAP, and CCR7 were significantly highly expressed in tumor tissue, while ZNF439 and KDM5D showed a similar trend." (PMID 40145017, 2025). "Consistent with the inhibition of CRACD mRNA by IFT57 in cells, IFT57 and CRACD mRNA had inverse correlations with survival in each of these tumor types." (PMID 39201643, 2024). "Analysis of The Cancer Genome Atlas datasets identified IFT57 as a top coexpressed gene with CD47 among 1156 human cancer cell lines and in most tumor types." (PMID 39201643, 2024). "Studies are also needed to determine the extent to which CD47 and IFT57 are coregulated in nonmalignant cells in the tumor microenvironment." (PMID 39201643, 2024). "This suggests that, in some tumor types, IFT57 rather than the coregulated CD47 mRNA expression could be the dominant driver of survival." (PMID 39201643, 2024).
cancer (3 papers, 2020 to 2024). A tumor composed of atypical neoplastic, often pleomorphic cells that invade other tissues. "Resisting cell death is one of the hallmarks of cancer that is associated with the IFT57 gene." (PMID 32613561, 2020). "A highly significant positive correlation was also observed between CD47 and IFT57 mRNA expression across the 1156 cell lines in the Cancer Cell Line Encyclopedia (CCLE) (p = 4.6 × 10−36)." (PMID 39201643, 2024). "IFT57 is a component of the primary cilium, which regulates signaling pathways critical for cancer progression." (PMID 39201643, 2024). "The present results confirm that at least two known pharmacologic regulators of CD47 mRNA expression in other cancers similarly regulate the expression of IFT57 mRNA." (PMID 39201643, 2024). "Taken together, these data indicate that IFT57 mRNA generally exhibits stronger correlations with improved or decreased cancer survival than CD47 mRNA expression." (PMID 39201643, 2024). "Examination of CD47 coexpressed genes in 29 TCGA cancer types identified IFT57 as a gene that is highly coexpressed with CD47 mRNA in carcinomas from multiple tissues." (PMID 39201643, 2024). "The antiphagocytic function of CD47 contributes to the association of poor survival with higher CD47 expression in some cancers, but we cannot exclude that coregulation of IFT57 also contributes to the survival deficits in tumors with high CD47 expression." (PMID 39201643, 2024). "The strong coexpression of CD47 and IFT57 mRNAs across carcinomas from multiple tissues suggests that engagement of these or other nearby enhancers by oncogenic transcription factors induces the expression of both genes." (PMID 39201643, 2024). "Because IFT57 showed stronger correlations than CD47 with poorer survival in several cancers, the assumption that the ‘don’t eat me’ function of CD47 accounts for such correlations may need to be reevaluated." (PMID 39201643, 2024). "CRACD has documented effects in other cancers, mediated by the cytoskeleton and β-catenin pathway, that could account for the altered migration and invasion of the IFT57 knockdown clones." (PMID 39201643, 2024). "Thus, known positive and negative transcriptional regulators of CD47 mRNA expression in cancer cells have parallel effects on IFT57 mRNA expression." (PMID 39201643, 2024). "Coexpression of CD47 and IFT57 mRNAs and correlations with overall survival in human cancers." (PMID 39201643, 2024). "Conversely, IFT57 was also the top co-expressed gene with CD47 in several carcinomas." (PMID 39201643, 2024). "Based on evidence for primary cilium functions in multiple cancers and the correlations between IFT57 expression and survival in several cancers, targeting the IFT57 and CD47 axes together may enhance the efficacy of the CD47-specific therapeutics currently in clinical trials." (PMID 39201643, 2024). "Additional studies are needed to determine whether CRACD and other targets of IFT57 identified here contribute to the correlations between CD47 mRNA expression and survival in various cancers." (PMID 39201643, 2024). "This suggests that mechanisms mediating IFT57 coregulation with CD47 are intrinsic to cancer cells, but this does not exclude additional contributions from IFT57 co-expression with CD47 mRNA in nonmalignant cells in stroma of the tumors analyzed in TCGA." (PMID 39201643, 2024). "Recent studies revealed CD47’s co-expression with IFT57 and its impact on cancer prognosis, suggesting dual targeting of CD47 and IFT57 may enhance efficacy and reduce CD47-targeted therapy’s side effects." (PMID 39652550, 2024). "Several signaling pathways have been identified that mediate the increased CD47 expression in specific cancers, but the possibility has not been considered that transcription regulators interacting with the promoter region of CD47 may simultaneously regulate expression of the adjacent IFT57." (PMID 39201643, 2024).
IFT57 also shares sentences with these, for which no sentence is quoted: ciliopathies (2 papers); orofaciodigital syndrome (2); brain disorder (1); epilepsy (1); genetic disease (1); hematologic malignancies (1); Huntington disease (1); intracranial hemorrhage (1); Joubert syndrome (1); leukemia (1); Meckel-Gruber syndrome (1); melanoma (1); neuroblastoma (1); prostate carcinoma (1); sarcoma (1); Senior-Loken syndrome (1); synpolydactyly (1); uveal melanoma (1).